ALK (ALK receptor tyrosine kinase)
Diseases named in the same sentence as ALK in open-access papers (continued):
Sharing a sentence is not in itself a finding about the gene and the disease.
neuroblastoma (continued). "Of note, resistance mutations in the ALK fusion proteins are generally found in the vicinity of the ATP-binding site, whereas in neuroblastoma the majority of the mutations are in activation segments of the kinase domain, such as the αC helix and the activation loop." (PMID 27483357, 2016). "ALK mutations at residues F1174, F1245 and R1275 are often referred to as ‘hot spot’ mutations, together accounting for more than 80% of all sporadic ALK mutations found in neuroblastoma." (PMID 27049722, 2016). "In addition to neuroblastoma, ALK amplification and mutation are reported in other types of cancers, including esophageal cancer, inflammatory breast cancer, colorectal cancer and rhabdomyosarcoma." (PMID 26802023, 2016). "Importantly, PF-06463922 abrogates ALK activity in the single-digit nanomolar range in all our different preclinical assays, including the neuroblastoma hot-spot mutations, ALKF1174, ALKF1245 and ALKR1275." (PMID 27483357, 2016). "Moreover, the role of ALK mutations in causing protein overexpression cannot be ruled out as one of the possible mechanisms, as previously documented in neuroblastoma." (PMID 26384210, 2015). "In addition to the numerous translocation events, gain of function ALK mutations have been observed in both spontaneous and hereditary neuroblastoma." (PMID 25955180, 2015). "Among the previously identified ALK somatic and germline mutations, we choose hot spot residues F1174L and R1275Q, since mutations at these sites account for more than 70% of mutations in neuroblastoma patients and result in a altered receptor activity." (PMID 26147305, 2015). "Although ALK mutations are found in a small percentage of neuroblastomas, other ALK activating aberrations may occur at genomic, or post-transcriptional or post-translational level (gene amplification, over expression, epigenetic regulation, phosphorylation)." (PMID 26299615, 2015). "ALK gene mutations are associated with both familial and sporadic neuroblastoma." (PMID 26010602, 2015). "Anaplastic Lymphoma Kinase (ALK) is also associated with cell survival signalling of neuroblastoma." (PMID 26010602, 2015). "Mutation of the ALK tyrosine kinase receptor occurs together with MYCN amplification in a subset of human neuroblastomas and may be one such tumor-promoting mutation." (PMID 26222553, 2015). "To decipher ALK function in neuroblastoma predisposition and oncogenesis, we have characterized knock-in (KI) mice bearing the two most frequent mutations observed in neuroblastoma patients." (PMID 24811913, 2014). "Retrospective analysis of historical pathological samples for ALK mutations should provide sufficient statistical power to shed a light on the vascular phenotype of neuroblastoma associated with ALK amplification, and each of the rare ALK mutations, including the lethal ALKF1174L mutation." (PMID 24667968, 2014). "ALK is an established causative oncogenic driver in neuroblastomas." (PMID 25188507, 2014). "The discovery of EML4-ALK fusion in 2007 as oncogenic driver in non-small-cell lung cancer (NSCLC) and next the identification of activating mutations in ALK gene in neuroblastoma made ALK one of the most extensively studied targets in the field of kinase inhibitor drug development." (PMID 24509625, 2014). "In addition, activating mutation of the tyrosine kinase ALK (anaplastic lymphoma kinase) was recently discovered in both familial and sporadic neuroblastomas." (PMID 25548681, 2014). "Yet, a syndromic presentation associating congenital neuroblastoma with severe encephalopathy and abnormal shape of the brainstem has now been described in two sporadic cases harbouring de novo germline F1174V and F1245V ALK mutations." (PMID 24811761, 2014). "The Th-ALKF1174L mutation leads to the constitutive activation of the ALK protein in neuroblastoma, and the vascular phenotype associated with amplified or wild-type (WT) ALK expression is currently unknown." (PMID 24667968, 2014).
neuroblastoma (continued). "Upon successful translation, intrinsic susceptibility MRI could provide a rapid method to identify children with ALK-driven tumors, enabling the stratification of children with this ultra high-risk neuroblastoma at the time of diagnosis." (PMID 24667968, 2014). "Finally, neither developmental abnormalities nor neurological disorders have been reported in patients with ALK germline activating mutations observed in a context of familial neuroblastoma, suggesting that these mutations are indeed less aggressive." (PMID 24811761, 2014). "Furthermore, a number of gain of function point mutations in ALK have been identified in neuroblastoma, pointing to the important role of ALK in driving tumour development." (PMID 24163262, 2013). "In addition, germline mutations resulting in familial neuroblastoma have been identified, including ALK and PHOX2B." (PMID 24349301, 2013). "Thus, pharmacological inhibition of STAT3 activity in neuroblastoma cell lines harboring ALK gain-of-function mutations results in reduced transcription of MYCN mRNA." (PMID 23889739, 2013). "According to our analysis, five out of the six crizotinib-resistant mutants and all 11 neuroblastoma-associated ALK missense mutations lead to a residue that can be observed in related proteins at the same position (in marked difference to driver mutations in EGFR)." (PMID 24376513, 2013). "However, comparison of ALK phosphorylation in SH-SY5Y and IMR-32 cells shed light on requirement to carefully investigate ALK phosphorylation in neuroblastoma, even after activating mutation identification." (PMID 22479414, 2012). "The ALK receptor is an attractive therapeutic target in several human cancers, including neuroblastoma in which the full length ALK molecule may be activated by point mutations." (PMID 22479414, 2012). "The identification of ALK mutations as potential drivers in neuroblastoma is significant for a portion of this cancer though overexpression of ALK may make a larger contribution to the malignant progression." (PMID 23267434, 2012). "Proteasome dependent degradation of mutated ALK suggests that use of Hsp90 inhibitors or HDAC inhibitors could be an attractive strategy to inhibit ALK dependent neuroblastoma proliferation." (PMID 22479414, 2012). "The Rohrer laboratory showed that neurogenesis is controlled by MK–ALK and proposed that this may explain some of the ligand-mediated, ALK-dependent neuroblastoma predisposition." (PMID 23267434, 2012). "Among the ALK transforming mutations reported in neuroblastomas, mutations at kinase domain residues F1174 and R1275 are the most frequently reported, and cells harboring these mutations have been shown to be sensitive to small molecule inhibitors of ALK in vitro." (PMID 22347506, 2012). "Indeed, a recent study shows that high levels of ALK expression supersede mutations of the receptor as a determinant of poor outcome of primary neuroblastoma." (PMID 23267434, 2012). "Amplification of the mutated gene, as observed for ALK in neuroblastoma, enhances this effect." (PMID 19226453, 2009). "However, mutations in kinases, except for ALK, are extremely rare in neuroblastoma." (PMID 41511287, 2025). "Furthermore, up to 20% of relapsed neuroblastoma cases may acquire druggable ALK mutations, which is another good reason to pursue tissue procurement every time the disease progresses or recurs in order to better accomplish rescue treatment strategies." (PMID 39409967, 2024). "Additionally, full-length ALK expression has been reported in cell lines and tumors, indicating oncogenic progression through overexpression or gain-of-function mutations, as recently observed in neuroblastoma cases." (PMID 38339401, 2024). "Aberrant activation of anaplastic lymphoma kinase (ALK) by activating point mutation or amplification drives 5–12% of neuroblastoma (NB)." (PMID 37686528, 2023).
neuroblastoma (continued). "Furthermore, relapsed neuroblastoma harbors increased somatic mutations, with enrichment of ALK-activating subclonal/clonal mutations compared to diagnostic tumors, with a frequency of 20% and rising as we sequence patient tumors and/or plasma more routinely at time of relapse." (PMID 37012551, 2023). "Furthermore, relapsed neuroblastoma harbors an increased proportion of somatic mutations, with enrichment of ALK activating mutations compared to diagnostic tumors, with a frequency of 20% and rising as we sequence patient tumors and/or plasma more routinely at the time of relapse." (PMID 37147298, 2023). "The initial optimism that ALK inhibitors could improve neuroblastoma outcome has been tempered by our recent understanding that the second most prevalent ALK mutation in sporadic neuroblastoma, ALK F1174L is intrinsically resistant to the first-generation ALK inhibitor, crizotinib." (PMID 35689207, 2022). "Moreover, ALK is mutated in approximately 10% of neuroblastomas." (PMID 33921066, 2021). "In addition, single-nucleotide variants in the ALK gene were detected in 9 out of 15 cell lines, including the F1174L mutation (in four cases) and the R1275Q mutation (in two cases), which are the most frequent ALK mutations in neuroblastoma." (PMID 34442335, 2021). "However, the potential role of this mutational process in tumor evolution in neuroblastoma could select these tumors for ALK or MEK inhibitors." (PMID 34479993, 2021). "In neuroblastoma, ALK amplification and gain-of-function mutations were found within the ALK tyrosine kinase domain including F1174L or R1275Q, the resulting protein could contribute to ALK autophosphorylation and activate downstream signaling in a monomer state." (PMID 32300555, 2020). "One possible mechanism through which ALK mutations may render neuroblastoma more aggressive is through increased MYCN activity resulting from PI3K-directed activation of ERK5 transcription levels or inhibiting GSK3ß-mediated repression of MYCN protein degradation." (PMID 31937834, 2020). "In neuroblastomas, high ALK expression was found to be associated with ALK amplification, as well as copy number gain of the ALK locus, supporting the hypothesis that ALK expression depends upon increasing the DNA dose; thus, we could expect a superimposable feature in NSCLC." (PMID 32664698, 2020). "Ten years ago, the identification of activating ALK mutations in a subset of sporadic and familial neuroblastoma cases revealed that ALK might represent a bona fide therapeutic target for precision medicine, analogous to other mutated tyrosine kinase receptors involved in various adult cancers." (PMID 31452835, 2019). "In addition to ALK fusions, mutation of ALK in pediatric neuroblastoma has been reported." (PMID 31334113, 2019). "The vast majority of NB tumors in children arise due to somatic mutations, as opposed to germline mutations of the anaplastic lymphoma kinase (ALK) gene in familial neuroblastoma, accounting for 2% of the cases." (PMID 31191243, 2019). "Consequently, neuroblastoma patients with ALK mutations show poorer overall survival." (PMID 31466397, 2019). "ALK gene copy number gains (3−5 copies/cell), especially ALK gene amplification (>6 copies/cell and/or clusters of signals) are well studied in other types of cancer, i.e., neuroblastoma, and are generally considered to be associated with aggressive tumor behavior and poorer outcomes." (PMID 31412611, 2019). "Importantly, in a subset of neuroblastoma patients, it has been documented that ALK activating mutations may be subclonal at diagnosis and at relapse." (PMID 31452835, 2019). "Although the specific kinase inhibitor crizotinib was not very effective in the treatment of patients with high-risk neuroblastoma or relapse, newly developed ALK inhibitors such as ceritinib or lorlatinib may be more effective in this malignancy and are now being evaluated in clinical trials." (PMID 30171420, 2018).
neuroblastoma (continued). "ALK missense mutations are detected in 8% of neuroblastoma (NB) tumors at diagnosis and confer gain-of-function oncogenic effects." (PMID 29535836, 2018). "The discovery of missense mutations of ALK gene identified this receptor tyrosine kinase as a therapeutic target in neuroblastoma (NB)." (PMID 28915608, 2017). "However, only one of 11 neuroblastoma patients with known ALK mutations responded in this study." (PMID 28425916, 2017). "ALK F1174 mutations arose as acquired resistance mutations in oncogenic ALK fusion proteins during crizotinib and ceritinib treatments, suggesting that F1174L may cause primary resistance to certain ALK inhibitors in neuroblastoma." (PMID 28425916, 2017). "A recent study of ALK aberrations in 1,596 diagnostic neuroblastomas showed that different ALK mutations confer differential oncogenic potential and sensitivity to Crizotinib, demonstrating the clinical relevance of mutational status for therapeutic stratification of ALK therapies for patients." (PMID 27888620, 2016). "Nevertheless, genes infrequently mutated but acting in molecular mechanisms underlying the oncogenesis and progression of neuroblastoma remain unknown, and targeted therapies identified to date, such as ALK inhibitors, might benefit a reduced number of patients." (PMID 27009842, 2016). "The discovery of activating mutations in the ALK gene in high-risk neuroblastoma (NB) has opened new opportunities for the development of novel therapeutic strategies against this often-fatal childhood cancer of the sympathetic nervous system." (PMID 25228590, 2014). "With crizotinib in pediatric phase I clinical trials, and other ALK inhibitor studies in development, a current challenge is to rapidly identify upfront children with high-risk ALK mutated or amplified neuroblastoma who may benefit from or become resistant to ALK-targeted therapy." (PMID 24667968, 2014). "To test whether functional interactions between NF1 and ALK exist in human cells, we used the SK-SY5Y and Kelly neuroblastoma cells, both of which harbor constitutively active F1174L ALK alleles, and both of which are highly sensitive to pharmacological ALK inhibition." (PMID 24278035, 2013). "CDX0239-PBD demonstrated ALK surface expression level-dependent cytotoxicity in neuroblastoma cell lines 5 days after treatment." (PMID 40813394, 2025). "Various genetic alterations have been identified in neuroblastoma, including amplification of MYCN, mutations in ALK, and segmental chromosomal changes." (PMID 41536427, 2025). "MES cells exhibit in vitro, more resistant to chemotherapeutics, retinoic acid, and ALK inhibition, drugs that are applied in current first- and second-line treatment protocols for patients with neuroblastoma." (PMID 40753395, 2025). "Most neuroblastomas express native ALK protein on the cell surface and ALK is uniformly overexpressed in fusion-positive rhabdomyosarcoma and in subsets of metastatic colorectal carcinoma, melanoma, ovarian carcinoma, and breast carcinoma." (PMID 40813394, 2025). "Recently, two studies demonstrated that ctDNA sequencing can detect genomic evolution in neuroblastomas under first-, second-, or third-generation ALK inhibitor therapy." (PMID 39760332, 2025). "The availability of ALK inhibitors, initially developed for adult cancers, has expedited the translation of this knowledge into targeted therapies for neuroblastoma." (PMID 40064818, 2025). "The synergistic treatment strategy involving MDM2 and ALK inhibition resulted in significant tumor regression in pediatric neuroblastoma PDX models." (PMID 39830019, 2025).
neuroblastoma (continued). "We then demonstrate that a humanized ALK-directed antibody conjugated to pyrrolobenzodiazepine (CDX0239-PBD) is internalized in ALK-expressing neuroblastoma cell lines with cell surface expression-dependent cytotoxicity." (PMID 40813394, 2025). "Longitudinally assessed TERT breakpoint and ALK p.R1275Q copy numbers were highly similar, possibly reflecting their origins in the same neuroblastoma clone." (PMID 39760332, 2025). "We also postulate that ALK functions as a tractable tumor-restricted antigen in other malignancies in addition to neuroblastoma." (PMID 40813394, 2025). "Lonafarnib has been tested incombination with ALK inhibitors in ALK-mutant neuroblastoma cells both in vitroand in vivo." (PMID 40771851, 2025). "For neuroblastomas with low ALK expression, an ALK inhibitor can increase ALK expression on tumor cells by preventing ALK internalization and degradation, thereby enhancing CAR-T cell-mediated cytotoxicity against tumors." (PMID 40072049, 2025). "In neuroblastoma with the ALK gene mutation F1174L, which confers resistance to crizotinib, the combination of 17-AAG with the ALK inhibitor TAE684 restored sensitivity to treatment." (PMID 41226319, 2025). "The failure of Th-Cre mediated deletion of Atrx to drive murine neuroblastoma is consistent with experiments in the Th-ALK models and it is likely that additional oncogenic drivers will be required to generate murine ATRX mutant neuroblastoma models." (PMID 39892705, 2025). "Roberto Chiarle’s team discovered that CAR-T cells targeting anaplastic lymphoma kinase (ALK) can effectively eliminate neuroblastomas with high ALK expression." (PMID 40072049, 2025). "TT sensitivity predictors were identified in 120/304 cases (39.5%): Tier II in 83 patients, Tier IB in 32 patients (almost always ALK in neuroblastoma, n = 31) and Tier IA in 5 patients: BRAF p.V600E (n = 3) and NF1 aberrations (n = 2)." (PMID 41373618, 2025). "PHOX2B binds to the ALK gene promoter and activates the Delta-Notch pathway to induce neuroblastoma cell proliferation." (PMID 40104501, 2025). "The origins of resistance to RTKi in neuroblastoma are poorly understood, and data on resistance in patients are available only for patients treated with ALK inhibitors." (PMID 41511287, 2025). "IRS2 nevertheless is of interest given that ALK uses IRS2 as an effector in neuroblastoma cells, possibly through AKT324 and its signaling control and effects are distinct from IRS140." (PMID 41253884, 2025). "The native anaplastic lymphoma kinase (ALK) oncofetal protein is expressed in neuroblastoma and in multiple pediatric and adult solid tumors." (PMID 40813394, 2025). "In 2008, the discovery of ALK aberrations in neuroblastoma marked a significant breakthrough, leading to the recognition of ALK as a target for tumors with activating ALK alterations." (PMID 40064818, 2025). "Esther R’s team showed that the acquisition of ALK compound mutations and mutations in members of the RAS-MAPK pathway is the mechanism by which ALK-driven neuroblastoma patients develop resistance to loratinib." (PMID 40115016, 2025). "We conclude that multiplexing markers will provide optimal disease surveillance for patients treated for very high–risk neuroblastoma, as performed for patient P3 by combining TERT breakpoint and ALK p.R1275Q marker surveillance in ctDNA." (PMID 39760332, 2025). "HDACs are also promising targets in solid tumours such as NSCLC32 and other ALK-related cancers such as neuroblastoma and lymphoma." (PMID 38465731, 2024). "Recently, promising clinical responses have been observed with the third‐generation ALK inhibitor lorlatinib in patients with neuroblastoma carrying ALK genetic alterations." (PMID 38877641, 2024). "In fact, recent discoveries pointed out the immunological properties of therapeutic strategies against ALK, such as ALK peptide vaccination in NSCLC and chimeric antigen receptor (CAR)-T cell therapy against ALK in neuroblastoma." (PMID 39767726, 2024).